ACSL4 (acyl-CoA synthetase long chain family member 4)
Diseases named in the same sentence as ACSL4 in open-access papers (continued):
Sharing a sentence is not in itself a finding about the gene and the disease.
cancer (continued). "In our study, we analyzed 14 genes that are significantly related to some or most anticancer drugs, such as FANCD2, HSPA5, NFE2L2, ACSL4, and DPP4 in the Cancer Therapeutic Response Portal Database." (PMID 35309947, 2022). "In xenograft models of athymic nude mice subcutaneously injected with shNT-GPX4-iKO cells and shNF2-GPX4-iKO cells, knockdown of NF2 upregulates TFRC, ACSL4 and nuclear YAP, and doxycycline-induced GPX4 knockdown is able to eliminate cancer lesions." (PMID 35847022, 2022). "Because of the upregulated expression of ACSL4 yet downregulated level of and FPN-1 and GPX4, 4T1 cell line demonstrated high ferroptosis sensitivity and was utilized for anti-cancer study." (PMID 32312987, 2020). "In this murine model, the overexpression of ACSL4 is preserved, probably indicating a predominant role of this ACSL/SCD component in cancer progression aspects." (PMID 31339921, 2019). "The robust protumor action of ACSL1/ACSL4/SCD network, together with the fact that all three of them are lipid metabolism enzymes, makes these druggable proteins attractive targets for cancer therapy." (PMID 26451612, 2015). "In this mechanism, ACSL4, LOX and COX-2 interact functionally and represent an integrated system that regulates the proliferation and metastatic potential of cancer cells." (PMID 21085606, 2010). "Moreover, the upregulation of ACSL4 by MYC, driven by oncogenic RTKs, increases cancer cells’ sensitivity to ferroptosis." (PMID 40732268, 2025). "ACSL4 knockout (ACSL4KO) cells exhibit significantly increased resistance to ferroptosis, and the enzyme is considered a potential therapeutic target in cancer." (PMID 41288931, 2025). "Studies have shown that lipid-enriched cancer cells exhibit increased expression of fatty acid oxidation (FAO) enzymes, such as carnitine palmitoyltransferase 1A (CPT1A) and acyl-CoA synthetase long-chain family member 4 (ACSL4), which sustain ATP production and confer resistance to apoptosis." (PMID 40282189, 2025). "In addition to ACSL1, ACSL4, and ACSL5, ACSL3 and ACSL6 also contribute to cancer progression, with their roles to be further elaborated in the context of specific cancers." (PMID 41288931, 2025). "Interestingly, high expression of ACSL4 positively correlated with cell survival and proliferation after REST perturbation, based on results of pan-cancer RNAi screen by the DepMap project." (PMID 38609948, 2024). "Besides, long-chain fatty acid-CoA ligase 4 (ACSL4) is involved in the activation of long-chain fatty acid metabolism and is reported to enhance the sensitivity of cancer cells to ferroptosis by promoting the accumulation of lipid peroxidation products." (PMID 38649701, 2024). "However, the correlation between the expression of ACSL4 and SLC7A11 in sera and cancer patients’ prognoses is still less explored in publications and remains controversial in several diseases." (PMID 39335604, 2024). "In particular, ACSL4, which ligates free polyunsaturated fatty acids (PUFAs) with coenzyme A to produce PUFA‐CoAs, which are subsequently incorporated into phospholipids (PLs) and are required for ferroptotic cancer cell death." (PMID 38140768, 2024). "Preclinical data clearly demonstrate that effects of ACSL4 on proliferation, migration and invasion of cancer cells are incremental rather than absolute." (PMID 37306503, 2023). "Owing to the heterogeneity of tumors, the role of ASCL4 in different cancers is not consistent, and the mechanism of ACSL4 in cancer promotion and inhibition is complex and variable." (PMID 37056351, 2023). "Moreover, acyl-CoA synthetase long-chain family member (ACSL4) regulates the function of METTL5 in fatty acid metabolism and thus facilitates cancer progression." (PMID 37055798, 2023).
cancer (continued). "When the level of ACSL4 is inhibited by siRNA, OA no longer has the ability to inhibit cancer cells." (PMID 37056351, 2023). "In addition to targeting ACSL4, miR-7-5p targets and blocks ALOX12 to inhibit lipid peroxidation and ferroptosis, leading to radio-resistance of cancer cells." (PMID 37686142, 2023). "ACSL4 (acyl-CoA synthetase long-chain family member 4) dictates sensitivity to ferroptosis and, usually, its expression is upregulated in some types of cancer rather than in healthy cells, determining a potential selectivity for cancer cells." (PMID 35628518, 2022). "The TPCI-induced ALOX12 activation resulted in direct peroxidation of PUFAs into lethal lipid ROS, which then accumulated and triggered cancer cells ferroptosis without the participation of ACSL4." (PMID 36517470, 2022). "In addition, almost all recent findings of PDT-induced ferroptosis are through the canonical ACSL4 and GPX4-related pathways, which are vulnerable to the heterogeneity of cancers." (PMID 36517470, 2022). "More strikingly, through expression modulation and activity inhibition, we have unveiled that TPCI-induced ferroptosis does not require the participation of ACSL4, and can be occurred on a variety of cancer cells with different ACSL4 expression levels." (PMID 36517470, 2022). "HK2‐induced ACSL4 led to FAO for the maintenance of stemness and self‐renewal in liver CSCs, which identified a previously uncharacterized molecular mechanism for HK2 in human cancer." (PMID 35603967, 2022). "As expected, ACSL4 was not consistently associated with levels of infiltration of CD8 T cells, Tfh, Treg, B cells, macrophages, NK, and DC across different cancers." (PMID 35126480, 2022). "In addition, ACSL4 mediates the level of immune cell infiltration in BRCA and SKCM, providing new ideas for personalized cancer immunotherapy." (PMID 35126480, 2022). "We have showed that TPCI can activate ALOX12 upon irradiation and enhance lipid ROS accumulation, hence promoting ferroptosis of cancer cells that does not require ACSL4." (PMID 36517470, 2022). "In addition, ACSL4 is a positive regulator in ferroptosis, whereas ACSL3 contributes to cancer cells acquiring ferroptosis resistance." (PMID 36497375, 2022). "Studies have shown that the activation of SRC proto-oncogene non-receptor tyrosine kinase (SRC) can inhibit cancer cell ferroptosis by inhibiting the expression of acyl-CoA synthetase long-chain family member 4 (ACSL4)." (PMID 35795552, 2022). "ACSL4 is one of the key enzymes involved in PUFA metabolism and plays roles in various pathological and physiological events such as neuronal development, steroidogenesis, and cancer exacerbation." (PMID 35103282, 2022). "Although modulation of ACSL4 may help to sensitize ferroptosis, the situation is usually complicated because the canonical ACSL4 and GPX4-related pathways are vulnerable to the heterogeneity of cancers." (PMID 36517470, 2022). "In addition, IL-15 is positively correlated with ferroptosis/cuproptosis-related genes (ACSL4 and LIPT1) in pan-cancer." (PMID 36467072, 2022). "Furthermore, we present a perspective on cancer therapies targeting or combining ACSL3 and ACSL4 in ferroptosis." (PMID 36497375, 2022). "Therefore, we further investigated connections between AKAP9, VPS13C, ACSL4, and HMOX2 expression and cancer metastasis." (PMID 33663112, 2021). "In addition, acyl-CoA synthetase long-chain family member 4 (ACSL4), a vital protein in ferroptosis, was overexpressed and served as an independent prognostic indicator in various cancers." (PMID 34335745, 2021). "Notably, the combination of ACSL4, LOX-5 and COX-2 inhibitors effectively inhibited the growth of these cancer cells in mice." (PMID 22808264, 2012).
cancer (continued). "Zhou et al42 explored the anti-cancer effects of PPIII on MDA-MB-231 human breast cancer cells both in vitro and in vivo and revealed that PPIII exerted anti-cancer activities mainly through ACSL4-mediated lipid peroxidation activation and ferroptosis induction." (PMID 40070365, 2025). "Recently, CYP1B1 was also shown to enhance the resistance of cancer cells to ferroptosis and immunotherapy, particularly anti-PD-1, through the activation of the protein kinase C (PKC) cascade and the degradation of acyl-CoA synthetase long-chain family member 4 (ACSL4)." (PMID 38001897, 2023). "Similarly, ACSL4 promotes HCC growth and enhances cancer cell stemness through lipid metabolism." (PMID 37372148, 2023). "However, the Janus-faced role of ACSL4 in cancers due to the diverse pathophysiology of cancers and the heterogeneous nature of tumors, make the lack of consistency becomes a problem to evaluate the indicative effect of biomarker ACSL4." (PMID 35910359, 2022). "Given that ALOX12 usually functions in many types of cancer cells, the discovery of TPCI as a photo-induced ALOX12 activator renders a viable therapeutic approach on the basis of distinct ferroptosis of cancer cells, without limiting to their intrinsic ACSL4 expression levels." (PMID 36517470, 2022). "Heat map showed that compounds with high similarity to ACSL4 included inhibitor of Insulin Growth factor 1 receptor protein Tyrosine kinase, nalbuphine opioid receptor agonist, opioid receptor antagonist, EGFR inhibitor, Cytochrome P450 inhibitor and carcinoma cell growth inhibitor." (PMID 35126480, 2022). "Lack of ACSL4 protected CD8+ T cells from the threat of high-dose RSL3-induced ferroptosis but also resulted in functional defects of CD8+ T cells, enabling cancer cells to evade the specific killing of CD8+ T cells." (PMID 38288118, 2023). "Although GPX4 is essential for cancer cells to escape from ferroptosis, inhibition of GPX4 fails to trigger ferroptosis in some cancer cells regardless of ACSL4 expression, suggesting the existence of additional mechanisms of ferroptosis resistance." (PMID 33868986, 2021). "Correspondingly, ACSL1 overexpression but not ACSL4 stimulated N-cadherin or Slug expression, well-known EMT markers involved in cancer invasion and metastasis." (PMID 28894242, 2017). "Additionally, analysis of 8 pairs of ccRCC cancer tissues and corresponding adjacent tissues revealed a negative correlation in SPI1 and ACSL4 expression levels." (PMID 41372608, 2025). "Moreover, ACSL4 was found to be more expressed in estrogen receptor (ER)-negative cancers, such as quadruple negative breast cancer (QNBC), than that in ER-positive cancers." (PMID 35910359, 2022).
infection (19 papers, 2016 to 2026). The state of being infected such as from the introduction of a foreign agent such as serum, vaccine, antigenic substance or organism. "The results indicated that the mRNA transcription levels of ACSL4 in the brain tissue of RH-infected mice were significantly reduced after 12 h post-infection." (PMID 40422259, 2025). "Infection by Coxsackievirus A6 (CV-A6) induces ferroptosis via ACSL4 to facilitate its replication in host cells." (PMID 40667873, 2025). "Quantitative analyses based on Pearson’s correlation coefficients further revealed the colocalization of dsRNA and ACSL4 at viral replication sites in ACSL4+/+ cells upon CV-A6 infection." (PMID 35038927, 2022). "Conversely, CV-A6 only induced lipid peroxidation 1.5-fold in ACSL4−/− cells compared with mock infection." (PMID 35038927, 2022). "Our findings revealed that after PbA infection, ACSL4 expression increased in splenocytes, while SLC7A11 and GPX4 expressions significantly decreased, indicating that malaria infection leads to iron homeostasis imbalance and elevated lipid peroxidation in the host." (PMID 41422632, 2025). "Moreover, lipid peroxidation in ACSL4+/+ cells was increased by approximately 4.5-fold after CV-A6 infection compared with the mock infection." (PMID 35038927, 2022). "Western blotting analysis revealed that PPRV infection suppressed the expression of SLC7A11 and GPX4, while increasing ACSL4 expression in EECs in a dose- and time-dependent manner." (PMID 40197059, 2025). "Molecular analyses revealed infection-induced downregulation of ferroptosis suppressor GPX4 and upregulation of pro-ferroptotic ACSL4 in macrophages and mice." (PMID 40667873, 2025). "At both the transcriptional and translational levels, T. gondii infection (MOI 1 or 10, 24 h post-infection) significantly upregulated SLC7A11, ACSL4, and COX2 compared to uninfected controls." (PMID 40667873, 2025). "Following infection with the PRU strain, the mRNA transcription levels of ACSL4 in both liver and brain tissues were significantly decreased." (PMID 40422259, 2025). "It is interesting to find that the cell death number was declined at 36 h of infection, the lipid peroxide MDA, ferrous iron, and ACSL4 were all attenuated at 36 h postinfection in accordance with GSH peak level." (PMID 35821227, 2022). "In the present study, we analyzed different time points of infection and found that ACSL1, ACSL3, ACSL4, ACSL5 and ACSL6 were all recruited into the lumen of the Ct inclusion as early as 6 hpi and as late as 24 hpi." (PMID 26988341, 2016). "albicans infection induced ferroptosis in vaginal tissues and macrophages, as manifested by lipid ROS accumulation, Fe2+ overload, GSH depletion, downregulation of GPX4 and SLC7A11, upregulation of ACSL4, 4-HNE, and MDA, and mitochondrial structural damage." (PMID 42072050, 2026). "Infection with SC1401 significantly upregulated the protein expression level of ACSL4, whereas infection with SC1401Δcdt did not affect the protein level." (PMID 40281583, 2025). "To further explore whether AMPK regulates BECN1 and other molecules, such as ACSL4 or GPX4, in the context of CAP-induced ferroptosis, we constructed a stable cell line with AMPK knockdown through lentivirus-mediated shRNA infection." (PMID 40438695, 2025).
kidney diseases (10 papers, 2020 to 2025). "It was reported that upregulation of the pro-ferroptotic protein long-chain fatty acid CoA ligase 4 (ACSL4) appeared in tubular cells in various human kidney diseases." (PMID 40182632, 2025). "The involvement of ACSL4 in the pathophysiology of kidney diseases, particularly AKI, is beginning to be described, and the emerging picture associates it with an injured phenotype and cell death." (PMID 38799564, 2024). "In this study, we found that the fibrotic kidney diseases, both in UUO/FA-induced mouse model and the TGF-β-induced HK-2 cell model, were associated with increased ferroptosis and upregulation of ACSL4." (PMID 37670055, 2023). "Up-regulation of ACSL4 expression was found in patients with acute kidney tubular injury, and ferroptosis plays an important role in the progression of renal diseases." (PMID 35103282, 2022). "We found that ferroptosis appeared in tubular epithelial cells (TECs) of various human kidney diseases and the upregulation of tubular proferroptotic gene ACSL4 was correlated with renal function in patients with acute kidney tubular injury." (PMID 32796819, 2020). "In conclusion, these results suggest ACSL4 is essential for tubular ferroptotic death during kidney fibrosis development and ACSL4 inhibition is a viable therapeutic approach to preventing fibrotic kidney diseases." (PMID 37670055, 2023). "Under such conditions, ACSL4 activity and ferroptotic cell death may be associated with maladaptive repair after AKI and chronic kidney epithelial injury, which is all the more relevant because IL-6 family cytokines are involved in the pathophysiology of kidney disease and drive tissue remodeling." (PMID 38799564, 2024).
metabolic disease (10 papers, 2014 to 2025). A congenital disorder (due to inherited enzyme abnormality) or acquired (due to failure of a metabolically important organ) disorder resulting from an abnormal metabolic process. "Obviously, further work will be required to determine the underlying mechanism(s) by which ACSL4 participates in the development of these metabolic diseases." (PMID 24879802, 2014). "The metabolic reprogramming mediated by ACSL4 has attracted widespread attention in metabolic disease research." (PMID 40086696, 2025). "The long-chain family of acyl-CoA synthetase proteins, which includes ACSL4, has recently been demonstrated to have a significant role in ferroptosis, and ACSL4 is a critical player in metabolic diseases." (PMID 36979479, 2023). "In addition, individuals with PDC, who have specific gene expression signatures (such as SOCS3, ACSL4, CLU, and ABCG1), are more susceptible to metabolic disorders." (PMID 34926685, 2021). "Moreover, further exploration of the role of ACSL4 in the pathophysiology of these metabolic diseases may identify novel targets that may be exploited in the development of new therapies to treat these clinical conditions." (PMID 24879802, 2014). "Consistent with the clinical observation that subjects with PDC tend to develop a metabolic disorder, series-clustering analysis detected several key lipid metabolic genes (PRKAR1A, ACSL4, SMPD3, etc.)." (PMID 34926685, 2021). "After determining that ACSL4 is highly expressed in the intestinal epithelial cells of IBD mice, promoting LPO and iron transport/metabolism disorder, we selected human normal colon epithelial cell line HCoEpiC to verify the repair effect of hucMSC-Ex on IBD in vitro." (PMID 37303049, 2023).
kidney (9 papers, 2022 to 2024). "Our findings suggested that ferroptosis occurs in diabetic liver injury and is associated with the upregulation of the initiator ACSL4." (PMID 39741964, 2024). "The toxin-induced HCC model involves a substantial degree of liver fibrosis, which is affected by ACSL4-dependent ferroptosis and discussed as a major contributor to liver carcinogenesis in the literature." (PMID 35963845, 2022). "In muti-omic analysis, gp78 overexpression led to up-regulation of lipogenesis genes, such as ACC1 and ACSL4, causing excess accumulation of lipids, especially PUFA-containing PEs, which could serve as the oxidized substance for ferroptosis during liver IR." (PMID 38065978, 2023). "Here, we confirmed that the downregulation of SOD, GSH, and GPX4 levels; the upregulation of Slc7a11, Acsl4, Cox2, 4-HNE, MDA, and Fe2+ levels; and kidney dysfunction all occur in the AKI mouse model." (PMID 35979396, 2022). "Similarly, given the sensitivity of ACSL4 as a promotor of lipid peroxidation, an initial study demonstrated that targeting inhibition of ACSL4 via dexmedetomidine protect kidneys against IRI-induced kidney injury." (PMID 39587094, 2024).
cardiovascular disease (5 papers, 2023 to 2026). "In contrast, ACSL4, which exerts effects opposite to ACSL3 in ferroptosis, is considered a risk factor in cardiovascular disease." (PMID 41288931, 2025). "In addition to the roles of ACSL3 and ACSL4 in cardiovascular disease via the ferroptosis pathway, further investigation of alternative pathways may provide additional insights into the contributions of these targets to cardiovascular pathology." (PMID 41288931, 2025).